NQO1 (NAD(P)H quinone dehydrogenase 1)
Description:
Flavin-containing quinone reductase that catalyzes two-electron reduction of quinones to hydroquinones using either NADH or NADPH as electron donors. In a ping-pong kinetic mechanism, the electrons are sequentially transferred from NAD(P)H to flavin cofactor and then from reduced flavin to the quinone, bypassing the formation of semiquinone and reactive oxygen species (By similarity). Regulates cellular redox state primarily through quinone detoxification. Reduces components of plasma membrane redox system such as coenzyme Q and vitamin quinones, producing antioxidant hydroquinone forms. In the process may function as superoxide scavenger to prevent hydroquinone oxidation and facilitate excretion. Alternatively, can activate quinones and their derivatives by generating redox reactive hydroquinones with DNA cross-linking antitumor potential. Acts as a gatekeeper of the core 20S proteasome known to degrade proteins with unstructured regions.
Synonyms: DTD; QR1; DIA4; NMOR1; DHQU; NMORI
Tractability: Small molecule: a drug acting on it is in phase 2 or 3 trials; a structure with a bound ligand is known; a high-quality ligand is known; it has a high-quality binding pocket; it belongs to a druggable protein family. PROTAC: UniProt records ubiquitination sites on it; ubiquitination databases record sites on it; a small molecule that binds it is known.
Target class: Enzyme; Oxidoreductase
Safety:
Unwanted effects reported when the protein is acted on. In parentheses: how it was acted on, where the effect was seen, and who reports it.
hemorrhage (source: ClinPGx)
Gene: Protein-coding gene on chromosome 16 (69,706,996 to 69,726,668, reverse strand). Ensembl gene ENSG00000181019.
Subcellular location: Cytoplasm, cytosol
Subcellular location (Human Protein Atlas): Cytosol
Pathways (Reactome):
Cellular responses to stimuli: NFE2L2 regulating anti-oxidant/detoxification enzymes
Chromatin organization: CHD6, CHD7, CHD8, CHD9 subfamily
Metabolism: Regulation of ornithine decarboxylase (ODC)
Gene Ontology:
Molecular function: identical protein binding; NADH dehydrogenase (quinone) (non-electrogenic) activity; NADPH dehydrogenase (quinone) activity; protein binding; RNA binding; cytochrome-b5 reductase activity, acting on NAD(P)H; NAD(P)H dehydrogenase (quinone) activity
Biological process: cell redox homeostasis; cellular response to oxidative stress; negative regulation of ferroptosis; negative regulation of protein catabolic process; removal of superoxide radicals; response to oxidative stress; ubiquinone metabolic process; vitamin E metabolic process; vitamin K metabolic process; nitric oxide biosynthetic process; response to toxic substance; synaptic transmission, cholinergic; xenobiotic metabolic process; innate immune response; protein catabolic process; protein polyubiquitination; response to lipopolysaccharide
Cellular component: cytosol; cytoplasm; nucleus; synapse
Genetic constraint (gnomAD): Loss-of-function variants: 25 observed, 28.3 expected, observed/expected ratio (o/e) 0.88, 90% interval 0.64 to 1.23. The upper end of that interval is the gene's LOEUF score, 1.23, which puts it in group 5 of 6, group 1 being the genes least tolerant of losing a copy. Missense variants: 266 observed, 341.82 expected, observed/expected ratio (o/e) 0.78, 90% interval 0.7 to 0.86. Synonymous variants: 106 observed, 123.84 expected, observed/expected ratio (o/e) 0.86, 90% interval 0.73 to 1.01.
Homologues: Orthologues: chimpanzee NQO1 (100% identical), macaque NQO1 (97% identical), pig NQO1 (89% identical), rabbit NQO1 (88% identical), dog NQO1 (87% identical), mouse Nqo1 (86% identical), rat Nqo1 (85% identical), guinea pig NQO1 (84% identical), tropical clawed frog nqo1 (63% identical), zebrafish nqo1 (50% identical). Paralogues in human: NQO2 (40% identical).
Diseases named in the same sentence as NQO1 in open-access papers:
NQO1 is named in the same sentence as 370 diseases in open-access papers, as found by Europe PMC text mining. Sharing a sentence is not in itself a finding about the gene and the disease. The quoted sentences say what the papers report.
breast carcinoma (95 papers, 2004 to 2026). "Collectively, these findings clearly indicate that aberrantly elevated NQO1 expression is associated with poor prognosis in patients with colorectal or breast cancer." (PMID 36793872, 2023). "MDA-MB-231 breast cancer cells, which lack NQO1 expression due to a *2 polymorphism, were found to be resistant to β-lap and DNQ." (PMID 38136388, 2023). "In gain-of-function experiments, NQO1 expression in NQO1-deficient MDA-MB-231 human breast cancer cells (MDA-MB-231/pNQO1 cells) induced a dramatic increase in cancer cell proliferation compared with parental NQO1-deficient MDA-MB-231/pCont cells." (PMID 36793872, 2023). "Conversely, ectopic overexpression of NQO1 in NQO1-deficient MDA-MB-231 breast cancer cells led to a marked increase in cell proliferation." (PMID 36793872, 2023). "MDA-MB-468 triple-negative breast cancer cells are deficient for NQO1, whereas T47D ER and PR positive luminal breast cancer cells express low levels of NQO1 with diminished activity." (PMID 35893874, 2022). "Previous studies have reported that high levels of NQO1 expression are associated with poor prognosis of breast cancer, gastric adenocarcinoma, and malignancy in pancreatic cancer." (PMID 34437536, 2021). "As expected, a breast cancer cell line derived from an individual expressing this NQO1 variant (MDA-MB-231) was largely resistant to CBK77 with an IC50 of >50 μM, which was very similar to the sensitivity of the cell line to the poorly active CBK07 analogue." (PMID 34615851, 2021). "NADPH quinone oxidoreductase 1 (NQO1) deficiency enhances the ROS production in oral and breast cancer due to mtDNA 4977 gene deletion." (PMID 34717757, 2021). "Because MCF-7 cells are heterozygous NQO1*1/NQO1*2, we decided to study the importance of the NQO1 polymorphism on the sensitivity of breast cancer cells to quinone-containing drugs." (PMID 31480790, 2019). "For instance, high-level expression of NQO1 appears to be associated with breast cancer progression." (PMID 31886179, 2019). "Rs1800566 (NQO1*2) was associated with poorer outcome in patients treated with anthracycline for breast cancer." (PMID 29970035, 2018). "Our findings further highlighted that the overexpression of NQO1 was associated with a decrease in the overall survival of breast cancer patients." (PMID 28578385, 2017). "In summary, NQO1 overexpression was linked with poor clinical outcome and was implicated in breast cancer progression." (PMID 28578385, 2017). "More specifically, higher levels of NQO1 mRNA strongly predict patient relapse in high-risk ER(+) breast cancer patients receiving endocrine therapy (mostly tamoxifen; H.R. > 2.15; p = 0.007)." (PMID 28411284, 2017). "We next investigated the NQO1 gain-of-function in MDA-MB-231 human breast cancer cells that are deficient in NQO1 expression." (PMID 27966538, 2016). "We identified a function of NQO1 in which HIF-1α stability was markedly enhanced under hypoxia following ectopic introduction of NQO1 into NQO1-deficient MDA-MB-231 breast cancer cells." (PMID 27966538, 2016). "Previously, we have shown that high expression of NQO1 protein was strongly associated with advanced stage, lymph node metastasis, Her2 overexpression and shortened survival of patients with breast cancer." (PMID 25885439, 2015). "In regard to survival, we previously found that high expression of NQO1 protein was strongly associated with advanced stage, lymph node metastasis, Her2 overexpression and shortened survival of patients with breast cancer." (PMID 25880877, 2015). "Currently there are only 3 studies in Asian population and 1 in Arab population for NQO1 Pro187Ser polymorphism and breast cancer risk." (PMID 24884893, 2014). "Several studies have previously suggested that the NQO1 Pro187Ser polymorphism was associated with an increased risk of breast cancer." (PMID 24884893, 2014).
breast carcinoma (continued). "The association between NQO1 Pro187Ser polymorphism and breast cancer risk was assessed by odds ratios (ORs) together with their 95% confidence intervals (CIs)." (PMID 24884893, 2014). "Our meta-analysis provides the evidence that the NQO1 Pro187Ser polymorphism contributed to the breast cancer susceptibility among Caucasians." (PMID 24884893, 2014). "In the past two decades, a number of molecular epidemiological studies have evaluated the association between the NQO1 Pro187Ser polymorphism and breast cancer risk, but the results remain inconsistent." (PMID 24884893, 2014). "The NQO1 Pro187Ser polymorphism was associated with an increased breast cancer risk among Caucasians (Ser/Pro vs. Pro/Pro: OR = 1.145, 95% CI = 1.008–1.301, P = 0.038; Ser/Ser + Ser/Pro vs. Pro/Pro: OR = 1.177, 95% CI = 1.041–1.331, P = 0.009)." (PMID 24884893, 2014). "In summary, NQO1 plays a key role in the progression of breast cancer, and high level of NQO1 protein is strongly associated with advanced stage, lymph node metastasis, Her2 overexpression and shortened survival of patients with breast cancer." (PMID 24499631, 2014). "Naturally occurring polymorphisms that reduce NQO1 expression are associated with higher rates of solid tumors, poor survival in breast cancer and carotid artery plaques in type II diabetes." (PMID 21483798, 2011). "The P187S polymorphism in NQO1 was associated with breast cancer in both populations from Tyrol and Prague with a higher risk for carriers of the 187S allele." (PMID 15138483, 2004). "NQO1 encodes a key metabolic enzyme that has been associated with breast cancer progression." (PMID 39030258, 2024). "Moreover, NQO1 polymorphism that leads to the enzyme inactivity has been found to be a strong prognostic and predictive factor in the poor outcome of breast cancer." (PMID 25880877, 2015). "Hence, we performed this meta-analysis including all available studies to provide the most comprehensive assessment of the associations between the NQO1 Pro187Ser polymorphism and breast cancer risk." (PMID 24884893, 2014). "The NQO1 Pro187Ser polymorphism was found to correlate with a lower enzymatic activity, which may result in increased incidence of carcinomas including breast cancer." (PMID 24884893, 2014). "All studies published from January 1966 to February 2014 on the association between NQO1 Pro187Ser polymorphism and breast cancer risk were identified by searching electronic databases PubMed, EMBASE, Cochrane library, and Chinese Biomedical Literature database (CBM)." (PMID 24884893, 2014). "Our study suggested that NQO1 Pro187Ser polymorphism might contribute to breast cancer risk, especially in Caucasian populations." (PMID 24884893, 2014). "High-level expression of NQO1 appears to be associated with breast cancer progression, and may be a potential biomarker for poor prognostic evaluation of breast cancers." (PMID 24499631, 2014). "Our results showed that the NQO1 is a candidate gene for breast cancer susceptibility." (PMID 24884893, 2014). "Recent studies reported association of NQO1 Pro187Ser polymorphism (rs1800566) with susceptibility to cancers such as gastric and breast cancers as well as with modification of the prognosis of breast cancer treated with anthracycline-based adjuvant chemotherapy." (PMID 25545243, 2014). "Of note, C609T NQO1 is known to enhance susceptibility to bladder and breast cancers." (PMID 20613985, 2010). "Thus, elevated levels of NQO1 expression could be used to identify high-risk ER(+) breast cancer patients, that might benefit from treatment with novel NQO1 inhibitors." (PMID 28411284, 2017).
breast carcinoma (continued). "Comparison of our data on the P187S polymorphism in NQO1 with those in the literature shows inconsistency, particularly with the one from Japan where the frequency for the 187S homozygotes was 16.5% in the controls and 14.3% in the breast cancer patients group." (PMID 15138483, 2004). "In contrast, in MCF7 breast cancer cells, NQO1 mRNA expression increased only at 24 h, while protein levels remained unchanged." (PMID 41531942, 2026). "The expression level of NQO1 in various tumor cells, especially glioma, lung cancer, colon cancer and breast cancer cells, is higher than that in normal tissues, the detection of NQO1 activity is important to understand tumor development mechanisms." (PMID 40630553, 2025). "For example, NQO1 [NAD(P)H: quinone oxidoreductase 1] expression in radiation-resistant breast cancer cells, had been positively regulated by lncRNA NEAT1." (PMID 39912983, 2025). "In contrast, the expression of NQO1 in a variety of tumor cells is much higher, especially glioma, lung cancer, colon cancer and breast cancer cells, than that in normal tissues cells." (PMID 40630553, 2025). "In a recent study, we showed that β‐Lap can instigate apoptosis in NQO1‐overexpressing breast cancer cells through PKA activation." (PMID 40014262, 2025). "Tumors with high NQO1 expression, such as hepatocellular carcinoma, pancreatic cancer, and breast cancer, are thus particularly sensitive to β-lapachone." (PMID 40051559, 2025). "Our previous study revealed that NQO1 was an essential regulator of altered glucose metabolism and contributed significantly to breast cancer progression." (PMID 39939940, 2025). "To establish the potential prognostic value of NQO1 in human cancer, we evaluated publicly available colorectal cancer and breast cancer datasets." (PMID 36793872, 2023). "STAT1 signaling pathway has been found to down-regulate quinone oxidoreductase 1 (NQO1), which function as ROS scavengers in breast cancer." (PMID 37748319, 2023). "To confirm these results, we additionally performed NQO1 gain-of-function experiments in MDA-MB-231 human breast cancer cells." (PMID 36793872, 2023). "In breast cancer, NQO1 expression is highly increased, and expression of CKS1B is also increased, albeit to a slightly lesser degree, but in both cases this increase is dependent on tumor stage." (PMID 36793872, 2023). "Immunohistochemical (IHC) analyses of colorectal and breast cancer tissues and cell lines used in this study demonstrated that high NQO1-expressing tumors frequently had IHC scores of 2.5 and 2.1 together with significantly elevated expression of CKS1." (PMID 36793872, 2023). "Further assessment of TCGA colorectal cancer and breast cancer databases supported correlations of high NQO1 and CKS1B expression with tumor stage." (PMID 36793872, 2023). "Previous Studies have shown that Lapatinib can inhibit tumor cell proliferation in breast cancer by increasing NQO1 expression." (PMID 37583897, 2023). "In this study, we utilized β-lap and AOA to assess their anti-cancer effects against four different breast cancer cell lines, only one of which strongly expressed NQO1." (PMID 35893874, 2022). "The in vitro cytotoxicity study was conducted on lung, prostate, and breast cancer cell lines (NQO1-overexpressing (NQO1 +) and NQO1-null H596, DU-145, and MDA-MB-231 cell lines)." (PMID 35903701, 2022). "The significant anti-proliferative effects on cancer cells induced by β-lap treatment have been shown in a variety of NQO1+ cancers including, lung, pancreatic, head and neck, prostate, colon, and breast cancers." (PMID 35893874, 2022). "Here, we report a novel combination with aminooxyacetic acid (AOA), a malate-aspartate shuttle (MAS) inhibitor, which enhances β-lap specific metabolic downregulation in NQO1+ breast cancer." (PMID 35893874, 2022). "NQO1 was highly expressed in diverse human cancers, including breast cancer, colon cancer, cervical cancer, and lung cancer." (PMID 35720178, 2022).
breast carcinoma (continued). "Enhanced expression of Nrf2 and its downstream genes HO1 and NQO1 after irradiation in breast cancer cells and their corresponding mammospheres ascertains the involvement of Nrf2 in radioresistance." (PMID 33419140, 2021). "We also employed mouse and human short hairpin RNAs (shRNAs) to silence NQO1 expression levels in multiple breast cancer cell lines." (PMID 34083537, 2021). "Collectively, these results demonstrate that STAT1-dependent signaling inhibits NQO1 expression in some breast cancer cells, sensitizing them to phenformin-induced oxidative stress." (PMID 34083537, 2021). "In particular, studies have shown that DMF can modulate the NRF2/HO1/NQO1 antioxidant signal pathway and inactivate NF-κB to suppress the growth of colon and breast cancer cells, and induce cell death." (PMID 33692690, 2021). "Although NQO1 is highly expressed in some cancers, including pancreatic, lung, and breast cancers, other cancer cells have lower NQO1 activity than normal cells." (PMID 32645959, 2020). "To further validate our findings in vivo, we performed immunohistochemical (IHC) staining of BQ and NQO1 on TMA constructed from 124 cases of primary breast cancers." (PMID 32110852, 2020). "It has been reported that expression of NQO1 in human breast cancer MCF-7c3 cells is induced after photodynamic therapy and that, consequently, the sensitivity of cancer cells to treatment with β-lapachone increases." (PMID 31388334, 2019). "The expression level of NQO1 is highly increased in various cancers, including prostate cancer, hepatocellular carcinoma, and breast-cancer, indicating an essential role of NQO1 in cancer development." (PMID 30513573, 2018). "To identify the function of NQO1 in the global change induced by β-lap treatment, we knocked down NQO1 in high-invasive breast cancer cell lines MCF-7 and MDA-MB-231." (PMID 28578385, 2017). "In accordance with our results, BNF acted as an NQO1 activity inducer in murine hepatoma Hepa1c1c7, human hepatoma HepG2, human breast cancer MCF7, and human prostate cancer LNCaP cells." (PMID 29144397, 2017). "As compared with normal breast tissues, both the mRNA and protein expression levels of NQO1 were greater in the breast cancer specimens." (PMID 28578385, 2017). "These empirical findings suggest that breast cancer patients with high NQO1 levels in tissue samples have a greater chance of metastasis and significantly shorter overall and disease-free survivals." (PMID 28578385, 2017). "The NQO1 protein and mRNA expression levels were higher in the invasive breast cancer cell lines than those in the non-invasive breast cancer cell lines." (PMID 28578385, 2017). "First, we confirmed the effects of NQO1 inhibition, and the results revealed that β-lap significantly inhibited NQO1 protein expression in over-expressed NQO1 breast cancer cells." (PMID 28578385, 2017). "Here, we demonstrated that NQO1 was elevated in breast cancer and that its expression level was positively correlated with invasion and reduced disease free survival (DFS) and overall survival (OS) rates." (PMID 28578385, 2017). "Next, we found that β-lapachone exerted significant anti-proliferation and anti-metastasis effects in breast cancer cell lines due to its effects on NQO1 expression." (PMID 28578385, 2017). "To further identify the role of NQO1 in the global changes induced by β-lap treatment, we knocked down NQO1 in high-invasive breast cancer cell lines MCF-7 and MDA-MB-231, then treated cells with β-lap." (PMID 28578385, 2017). "In this study, we revealed that the overexpression of NQO1 was significantly correlated with metastasis in breast cancer specimens." (PMID 28578385, 2017).